SLCO2A1 (solute carrier organic anion transporter family member 2A1)
Diseases named in the same sentence as SLCO2A1 in open-access papers (continued):
Sharing a sentence is not in itself a finding about the gene and the disease.
gastric cancer (3 papers, 2020 to 2022). A primary or metastatic malignant neoplasm involving the stomach. "Moreover, colocalization of this transporter and the PGE2 receptor EP4 has been detected in the mucosa of both normal stomach and gastric carcinoma, suggesting a role of SLCO2A1 in the PGE2-mediated cellular effects." (PMID 33081378, 2020).
myelofibrosis (3 papers, 2015 to 2023). A partial or complete replacement of the bone marrow stroma by fibrous tissue. "Some studies suggested that PHO patients with prostaglandin transporter SLCO2A1 mutations were more likely to develop myelofibrosis, which might explain the high incidence of myelofibrosis in PHO patients with GI involvement." (PMID 31878983, 2019).
ovarian carcinoma (3 papers, 2018 to 2022). A malignant neoplasm originating from the surface ovarian epithelium. "In ovarian cancer, both increased and reduced levels of SLCO2A1 have been reported." (PMID 33081378, 2020). "Notably, ubiquitously expressed SLCO2A1, SLCO2B1, SLCO3A1, and SLCO4A1 genes have been identified in ovarian cancer." (PMID 30131693, 2018).
adenoma (2 papers, 2013 to 2021). A neoplasm arising from the epithelium. "As for BTN-specific SE-adjacent genes identified in this study, SLCO2A1 was reported to be downregulated in follicular thyroid cancer than benign adenoma, suggesting its role in thyroid tumor pathogenesis." (PMID 34179011, 2021). "We confirmed that ELMO1, EMCN, ITIH5, KCNAB1, and SLCO2A1 were downregulated in follicular carcinoma compared to adenoma." (PMID 24099521, 2013).
diabetic foot ulcers (2 papers, 2022 to 2024). "In contrast, diabetes patients with diabetic foot ulcers have locally upregulated expression of SLCO2A1 and, consequently, have highly reduced extracellular PGE2 levels associated with impaired wound healing due to inability to activate EP4 receptors." (PMID 38783936, 2024). "SLCO2A1 has been revealed to play a key role in many pathophysiological processes and is considered a potential pharmacological target for the treatment of diabetic foot ulcers." (PMID 35401672, 2022).
enteritis (2 papers, 2020). Inflammation of the small intestine. "Although a recent study has demonstrated that SLCO2A1 function is lost in patients with CEAS12, the current study revealed that Slco2a1-deficient mice did not spontaneously develop enteritis." (PMID 32184453, 2020). "Further, although recent studies have shown that SLCO2A1 function is lost in patients with CEAS, Slco2a1-deficient mice do not spontaneously develop enteritis." (PMID 33166338, 2020). "Thus, given the protective effect of PGE2 on mucosal injury, PGE2 seems to exert contrasting effects on the intestinal mucosa, and the mechanisms underlying enteritis development under SLCO2A1 deficiency have not been clarified." (PMID 32184453, 2020). "Deletion of Slco2a1 did not cause alteration of epithelial structure and spontaneous enteritis." (PMID 32184453, 2020).
glaucoma (2 papers, 2021 to 2022). Increased pressure in the eyeball due to obstruction of the outflow of aqueous humor. "To date, the response to latanoprost of patients with glaucoma and ocular hypertension, is reported to be associated with the genetic polymorphism of seven genes (ABCB1, SLCO2A1, AFAP1, GMDS, PTGS1, MRP4, and PTGFR)." (PMID 36313286, 2022). "Rs1045642 in ABCB1, rs4241366 in SLCO2A1, rs9503012 in GMDS, rs10306114 in PTGS1, rs11568658 in MRP4, rs10786455 and rs6686438 in PTGFR were reported to be positive with the response to prostaglandin analogs in patients with glaucoma." (PMID 36313286, 2022).
Hypertension (2 papers, 2015 to 2019). The presence of chronic increased pressure in the systemic arterial system. "In another independent replication cohort consisting of 3,183 African American samples from Hypertension Genetic Epidemiology Network (HyperGEN) and the Genetic Epidemiology Network of Arteriopathy (GENOA), the top genes achieved P-values of 0.04 (ITGA7), 0.08 (SLCO2A1), and 0.02 (POT1)." (PMID 30863429, 2019).
acromegaly (1 paper, 2023). Acromegaly is an acquired disorder related to excessive production of growth hormone (GH) and characterized by progressive somatic disfigurement (mainly involving the face and extremities) and systemic manifestations. "We describe a Japanese male patient with PDP who was differentially diagnosed with acromegaly by identification of compound heterozygous variants in SLCO2A1." (PMID 36968251, 2023).
bone hypertrophy (1 paper, 2024). "The responsible genes, hydroxyprostaglandin dehydrogenase (HPGD) and solute carrier organic anion transporter family member 2A1 (SLCO2A1), have been identified, leading to an understanding of the etiology and the development of treatment for skin and bone hypertrophy." (PMID 38500951, 2024).
cardiopulmonary diseases (1 paper, 2025). "However, unlike SHO, which is secondary to severe cardiopulmonary diseases or malignancies, PHO is a rare genetic disorder caused by mutations in the hydroxyprostaglandin dehydrogenase (HPGD) gene or the solute carrier organic anion transporter family member 2A1 (SLCO2A1) gene." (PMID 40251683, 2025).
chronic asthma (1 paper, 2026). An asthma that is characterized by the development of persistent airway inflammation and recurrent attacks of breathlessness and wheezing, which vary in severity and frequency. "Here, we present cryogenic electron microscopy structures of SLCO2A1 bound to endogenous PGs and to four widely prescribed medications for treating inflammation, chronic asthma, and Parkinson's disease (PD)." (PMID 41862483, 2026).
colorectal tumour (1 paper, 2017). "Certainly future studies, are necessary to establish a clear relationship between SLCO2A1 expression in colorectal tumours and disease survival." (PMID 29185482, 2017).
Cronkhite-Canada syndrome (1 paper, 2021). Cronkhite-Canada syndrome (CCS) is a rare gastrointestinal (GI) polyposis syndrome characterized by the association of non-hereditary GI polyposis with the cutaneous triad of alopecia, nail changes and hyperpigmentation. "Cronkhite-Canada syndrome (CCS), chronic enteropathy associated with SLCO2A1 gene (CEAS), and intestinal Behçet’s disease (BD) are classified as intractable intestinal disorders in Japan." (PMID 32092751, 2021). "Cronkhite-Canada syndrome (CCS), chronic enteropathy associated with SLCO2A1 gene (CEAS), and intestinal Behçet’s disease (BD) are rare intestinal disorders classified as intractable diseases in Japan." (PMID 32092751, 2021).
Diarrhea (1 paper, 2025). Abnormally increased frequency (usually defined as three or more) loose or watery bowel movements a day. "CEAS/CNSU caused by SLCO2A1 defects, as well as congenital/familial diarrhea associated with SLC26A1, SLC9A3, and GUCY2C mutations, were the most prevalent monogenic disorders in patients with LO-mIBD, significantly more common than in those with IO-mIBD (p < 0.001)." (PMID 40474095, 2025).
fibrosis (1 paper, 2015). the formation of excess fibrous connective tissue in an organ or tissue in a reparative or reactive process. "In conclusion, pulmonary PGE2 disposition is largely regulated by SLCO2A1, demonstrating that SLCO2A1 plays a critical role in protecting the lung from BLM-induced fibrosis." (PMID 25923111, 2015).
gastric tumors (1 paper, 2020). "The authors presume that this homeostasis is impaired in gastric tumors due to the negative regulation of SLCO2A1 and, consequently, the negative regulation of PGE2 degradation, resulting in the enhancement of PGE2 signaling and gastric tumorigenesis." (PMID 33081378, 2020).
GI hemorrhage (1 paper, 2019). "In a study including 43 Chinese patients, watery diarrhea occurred in more than half of the patients with either HPGD or SLCO2A1 gene mutation, but SLCO2A1 mutated patients had a higher frequency of GI hemorrhage." (PMID 31878983, 2019).
Hyperhidrosis (1 paper, 2023). Abnormal excessive perspiration (sweating) despite the lack of appropriate stimuli like hot and humid weather. "Patients carrying homozygous SLCO2A1 mutations develop clubbing of fingers and toes during or after puberty and hyperhidrosis of palms and soles." (PMID 36833358, 2023).
hypopharyngeal squamous cell carcinoma (1 paper, 2025). "Additionally, the same authors recently reported that ST reveal the correlation between the TIME and overexpression of SLCO2A1 with tumor suppression in hypopharyngeal squamous cell carcinoma." (PMID 40264779, 2025).
inflammatory bowel disease (1 paper, 2024). A spectrum of small and large bowel inflammatory diseases of unknown etiology. "Chronic enteropathy associated with SLCO2A1 gene (CEAS) is a unique type of inflammatory bowel disease." (PMID 38890589, 2024).
intestinal polyp (1 paper, 2017). Discrete abnormal tissue masses that protrude into the lumen of the intestine. "Notably, the endothelial marker CD34 (a marker of endothelial vasculature), was significantly lower in the stromal tissue of intestinal polyps from Slco2a1-deficient ApcΔ716/+ mice." (PMID 29185482, 2017). "The extent of the CD34-positive area was compared in intestinal polyps between the Slco2a1+/+/Apc∆716/+ and Slco2a1−/−/ApcΔ716/+ mice." (PMID 29185482, 2017).
ischemia (1 paper, 2024). A hypoperfusion of the BLOOD through an organ or tissue caused by a PATHOLOGIC CONSTRICTION or obstruction of its BLOOD VESSELS, or an absence of BLOOD CIRCULATION. "Here we hypothesize that SLCO2A1 loss-of-function mutations might cause vascular function alterations or ischemia, leading to vasodilation and fibrotic proliferation in intestinal lesions, which hopefully may provide clues to the future pathogenic mechanism of CEAS." (PMID 38755710, 2024).
metastatic tumors (1 paper, 2025). "SLCO2A1 was positively correlated with EC, but negatively with SC and IPS in metastatic tumors." (PMID 40943183, 2025).
Parkinson disease (1 paper, 2020). A progressive degenerative disorder of the central nervous system characterized by loss of dopamine producing neurons in the substantia nigra and the presence of Lewy bodies in the substantia nigra and locus coeruleus. "Mutations in PINK1, which codes for a kinase involved in mitochondrial quality control, are associated with Parkinson’s disease; mutations in SLCO2A1, a prostaglandin transporter, cause chronic enteropathy." (PMID 33239447, 2020).
polyp (1 paper, 2017). A usually exophytic mass attached to the underlying tissue by a broad base or a thin stalk. "Immunohistochemical analysis was performed to determine Oatp2a1 expression in normal small intestine and colon compared to polyp in the small intestine of Slco2a1+/+/ApcΔ716/+ mice." (PMID 29185482, 2017).
premature ovarian failure (1 paper, 2018). "The PHO-causing SLCO2A1 mutation-carrying female indeed presented the premature ovarian failure and the extremely early menopause with altered hormone levels." (PMID 30352415, 2018).
prostate carcinoma (1 paper, 2020). A carcinoma that arises from epithelial cells of the prostate gland. "Therefore, SLCO2A1 may be an attractive target in prostate cancer." (PMID 32103057, 2020).
pulmonary fibrosis (1 paper, 2015). Chronic progressive interstitial lung disorder characterized by the replacement of the lung tissue by connective tissue, leading to progressive dyspnea, respiratory failure, or right heart failure. "Since the lung concentration of anti-fibrotic PGE2 was likely reduced in Slco2a1-/- mice, we further studied the association of SLCO2A1 with pulmonary fibrosis induced by BLM." (PMID 25923111, 2015). "Loss of function of SLCO2A1 could cause aggravation of pulmonary fibrosis, where activation of fibrotic signaling via PKCδ was involved in collagen deposition." (PMID 25923111, 2015). "Since BLM-induced pulmonary fibrosis was exacerbated in Slco2a1-/- mice with Cox-2 and 15-Pgdh expression unchanged, SLCO2A1 itself is considered to be an independent determinant of local PGE2 concentration." (PMID 25923111, 2015). "The pathological relevance of SLCO2A1 was further studied in mouse BLM-induced pulmonary fibrosis models." (PMID 25923111, 2015). "Future work is warranted to determine alveolar lumen and interstitial tissues by the use of more sophisticated analytical techniques (e.g. microdialysis) during development of pulmonary fibrosis to prove this pathophysiological role of SLCO2A1." (PMID 25923111, 2015). "The present study aimed to evaluate the pathophysiological relevance of SLCO2A1 to bleomycin (BLM)-induced pulmonary fibrosis in mice." (PMID 25923111, 2015). "Slco2a1 deficiency resulted in retention of PGE2 in alveolar lumen and aggravated pulmonary fibrosis in mice treated with BLM." (PMID 25923111, 2015). "Histological examination indicated more severe pulmonary fibrosis in Slco2a1-/- than in WT mice, with thickened interstitial connective tissue." (PMID 25923111, 2015). "Therefore, the present study was designed to investigate the role of SLCO2A1 in PGE2 disposition by means of a study of BLM-induced pulmonary fibrosis in Slco2a1-/- and wild-type (WT) mice." (PMID 25923111, 2015).
tumor (16 papers, 2014 to 2025). "The large polyps from the Slco2a1−/−/Apc∆716/+ mice had significant reductions in microvascular density, consistent with the high expression of Slco2a1 in the tumour-associated vascular endothelial cells." (PMID 29185482, 2017). "It was indicated that the N-M tumor metastasis pattern and a putative ovarian origin, rather than tubular origin, are associated with a more favorable prognosis, which would be in line with a role of SLCO2A1 and HPGD implicated in the degradation of pro-inflammatory prostaglandins." (PMID 30131693, 2018). "Firstly, relative genes involved in PGD2 signaling axis, HPGDS, PTGDS, PTGDR and SLCO2A1, were all significantly lower expressed in tumor lung tissue compared to normal in TCGA-LUAD cohort." (PMID 40474982, 2025). "The expression of PTGDS, PTGDR and SLCO2A1 also shows a decreasing trend across normal lung, tumor lung, and metastatic brain tissues, as well as in early and advanced stages and at different differentiation levels." (PMID 40474982, 2025). "More specifically, PGD2 plays a pivotal role in signaling through its associated aixes, such as PGD2 ∼ SLCO2A1 and PGD2 ∼ PTGDR, suggesting potential metabolic implications in tumorigenesis, tumor invasion and metastasis." (PMID 40474982, 2025). "We found an upregulation for the PTGS2 gene mean factor of 2.51 and a downregulation for the HPGD and SLCO2A1 genes (mean factor of 0.10 and 0.37, respectively) in tumorous mucosa in a gender-independent manner." (PMID 33081378, 2020). "Reduced SLCO2A1 expression has been associated with increasing PGE2 levels in the tumor microenvironment and, consequently, with tumor angiogenesis in GC." (PMID 33081378, 2020). "Notably, some of these genes, including FTH1 and SLCO2A1, play pivotal roles in tumour progression." (PMID 39393173, 2024). "While the comparison of expression data between tumor and normal samples showed that 8 out of 36 ARGs were significantly differentially expressed, including CCND2, CXCL6, KCNJ8, LPL, SERPINA5, SLCO2A1, VTN, and APOH." (PMID 35836112, 2022). "Non-tumor components included endothelial cells (expressing VWF, CDH5, ECSCR, SLCO2A1, and MYCT1), pericytes (marked by RGS5, MCAM, and PDGFRB), normal oligodendrocytes (showing PTGDS, MBP, TF, and MOG expression), and TAMs (identified by CD14, AIF1, FCER1G, FCGR3A, TYROBP, and CSF1R)." (PMID 41394801, 2025). "It is conceivable that PGE2 is elevated in the extracellular space of Slco2a1-null tumours, however, at this time we are not able to reliably measure the PGE2 in the extracellular space of tumours." (PMID 29185482, 2017).
cancer (14 papers, 2014 to 2025). A tumor composed of atypical neoplastic, often pleomorphic cells that invade other tissues. "Elevated expression of SLCO2A1 has been linked to increased intra-tumoral prostaglandins, contributing to several cancer hallmarks and supporting a cancer stem cell-like phenotype." (PMID 38534987, 2024). "SLCO2A1 expression is documented in several cancers including BC where, overall, it appears expression may be increased." (PMID 32388639, 2020). "Therefore, we predicted that inhibiting the prostaglandin transporter SLCO2A1 may selectively kill cancer cells." (PMID 32103057, 2020). "Then, we explored the TTK, C16orf54, PPAT, CD3EAP, SLCO2A1, ACAT1, and GAS2L3 genes in the CBioPortal for cancer genomics." (PMID 33402113, 2021). "In line with this, a recent study showed that the PG importer PGT (SLCO2A1) is involved in the loading of exogenous PGE2 into intracellular compartments in murine macrophages and human cancer cells resulting in elevated secretion of PGE2 via exocytosis." (PMID 35126121, 2021). "Currently, no anticancer drugs are known to be transported by SLCO2A1; however, expression is known to be variable in cancer tissues." (PMID 32388639, 2020). "Regarding PGE2 transporters, there is a lack of information, but SLCO2A1 downregulation and/or ABCC4 overexpression have been found in some cancers." (PMID 33081378, 2020). "Six genes (SLCO2A1, MGAT4B, SLC25A33, MCCC1, OIP5, and CTHRC1) have been shown to affect the tumorigenesis of other cancer types but not PC." (PMID 30024105, 2018). "The results showed that RGS2 and DUSP1 were significantly expressed in the cell population, and three model genes, CXCR4, SLCO2A1, and FNDC1, were not in the cluster, indicating that the two model genes that were significantly expressed could be used as marker genes of cancer." (PMID 36591293, 2022).
genetic disorder (3 papers, 2018 to 2026). "Chronic enteropathy associated with SLCO2A1 gene (CEAS) is a hereditary disease caused by mutations in the SLCO2A1 gene and characterized by multiple small intestinal ulcers of nonspecific histology." (PMID 29313109, 2018).
gastrointestinal disease (2 papers, 2007 to 2024). A disease that occurs in the gastrointestinal system, excluding the hepatobiliary system. "CEAS, as a rare SLCO2A1 gene-related gastrointestinal disease, is still not fully and deeply understood by clinicians as well as researchers, from its clinical features in various populations to its pathogenesis." (PMID 38755710, 2024).
intestinal disease (2 papers, 2021 to 2024). "Chronic enteropathy associated with SLCO2A1 gene (CEAS) is a rare monogenic disease characterized by multiple intestinal ulcers due to loss-of-function mutations in SLCO2A1 gene." (PMID 38755710, 2024). "Chronic enteropathy associated with SLCO2A1 gene is a rare intestinal disease caused by loss-of-function SLCO2A1 mutations, with clinical and genetic characteristics remaining largely unknown, especially in Chinese patients." (PMID 38755710, 2024).
autosomal recessive inherited disease (1 paper, 2018). "PHO is an autosomal recessive inherited disease that is classified into two subtypes based on its causal gene, one being the HPGD gene and the other the SLCO2A1 gene." (PMID 29313109, 2018).
colorectal (1 paper, 2014). "The rs6839448C>A and rs7617492G>A tagSNPs in SLCO2A1 were implicated in colorectal carcinogenesis Furthermore, individuals carrying the haplotype containing both the A and G alleles of rs6839448 and rs7617492 tagSNPs (TAGAAC), respectively, had a nearly 50% protection for CRC." (PMID 24694755, 2014).
digestive system diseases (1 paper, 2025). "CO patients were more susceptible to digestive system diseases, potentially related to their prevalent SLCO2A1 mutations, which cause both PHO and chronic intestinal diseases." (PMID 40251683, 2025).
muscular disorders (1 paper, 2021). "SLCO2A1 in both transporter and channel modes is expected to serve as a perspective pharmacological target for developing new therapeutics for treatment of both inherited and acquired skin, bone, gut, neuronal, and muscular disorders, as well as malignancies involving SLCO2A1." (PMID 34073084, 2021).